RNU6-402P (RNA, U6 small nuclear 402, pseudogene)
Gene: Small nuclear RNA gene on chromosome 5 (98,889,731 to 98,889,833, forward strand). Ensembl gene ENSG00000222610.
Homologues: Orthologues: chimpanzee U6 (98% identical), macaque U6 (92% identical), pig U6 (83% identical), dog U6 (80% identical), mouse Gm22345 (73% identical). Paralogues in human: RNU6-166P (86% identical), RNU6-38P (86% identical), RNU6-41P (86% identical), RNU6-477P (86% identical), RNU6-142P (85% identical), RNU6-15P (85% identical), RNU6-574P (85% identical), RNU6-1011P (84% identical), RNU6-1117P (84% identical), RNU6-1145P (84% identical), RNU6-1158P (84% identical), RNU6-12P (84% identical), and 1288 more.